NBEAL2 (neurobeachin like 2)
Description:
Probably involved in thrombopoiesis. Plays a role in the development or secretion of alpha-granules, that contain several growth factors important for platelet biogenesis.
Synonyms: KIAA0540; BDPLT4; GPS
Tractability: Antibody: its Gene Ontology location is reachable by antibodies, with high confidence. PROTAC: ubiquitination databases record sites on it; its protein half-life has been measured.
Gene: Protein-coding gene on chromosome 3 (46,979,666 to 47,009,707, forward strand). Ensembl gene ENSG00000160796.
Subcellular location: Endoplasmic reticulum
Pathways (Reactome):
Immune System: Neutrophil degranulation
Gene Ontology:
Molecular function: protein binding
Biological process: platelet formation; myeloid cell differentiation
Cellular component: endoplasmic reticulum; cytosol; ficolin-1-rich granule membrane; membrane; plasma membrane; tertiary granule membrane
Genetic constraint (gnomAD): Loss-of-function variants: 159 observed, 282.97 expected, observed/expected ratio (o/e) 0.56, 90% interval 0.49 to 0.64. The upper end of that interval is the gene's LOEUF score, 0.64, which puts it in group 2 of 6, group 1 being the genes least tolerant of losing a copy. Missense variants: 3,100 observed, 3,571.2 expected, observed/expected ratio (o/e) 0.87, 90% interval 0.84 to 0.89. Synonymous variants: 1,488 observed, 1,511.9 expected, observed/expected ratio (o/e) 0.98, 90% interval 0.94 to 1.03.
Gene-disease validity (ClinGen):
ClinGen rates the evidence that NBEAL2 causes each of these diseases.
gray platelet syndrome (autosomal recessive): Definitive. Gray platelet syndrome (GPS) is a rare inherited bleeding disorder characterized by macrothrombocytopenia, myelofibrosis, splenomegaly and typical gray appearance of platelets on Wright stained peripheral blood smear.
Homologues: Orthologues: chimpanzee NBEAL2 (99% identical), macaque NBEAL2 (93% identical), rabbit NBEAL2 (91% identical), dog NBEAL2 (89% identical), rat Nbeal2 (89% identical), pig NBEAL2 (89% identical), mouse Nbeal2 (88% identical), guinea pig NBEAL2 (87% identical), tropical clawed frog nbeal2 (59% identical), zebrafish nbeal2 (55% identical), Caenorhabditis elegans sel-2 (17% identical), Caenorhabditis elegans wdfy-3 (16% identical). Paralogues in human: NBEAL1 (46% identical), WDFY4 (20% identical), WDFY3 (20% identical), NBEA (19% identical), LRBA (19% identical), LYST (17% identical), NSMAF (10% identical).
Diseases named in the same sentence as NBEAL2 in open-access papers:
NBEAL2 is named in the same sentence as 38 diseases in open-access papers, as found by Europe PMC text mining. Sharing a sentence is not in itself a finding about the gene and the disease. The quoted sentences say what the papers report.
gray platelet syndrome (17 papers, 2013 to 2026). "Mutations in NBEAL2 were identified in Gray Platelet Syndrome (GPS) patients, whose platelets appear gray on electron microscopy images due to the absence of α-granules." (PMID 40309239, 2025). "A genetic analysis validated the pathogenic homozygous mutation c.5257C>T in the NBEAL2 gene, which corresponds to gray platelet syndrome." (PMID 38060757, 2023). "The first RNA-seq-enabled discovery for an IPD was the identification of NBEAL2 variants as the cause of gray platelet syndrome using platelet RNA-seq." (PMID 35886993, 2022). "Abnormal reads were detected, showing intron retention in NBEAL2 for platelets from a gray platelet syndrome patient due to a splice variant." (PMID 35886993, 2022). "In 5 out of 47 Gray platelet syndrome patients (a milder bleeding disorder) with new variants in NBEAL2, 123 platelet proteins were mostly downregulated, with the majority being α-granule-associated and cargo proteins at unaltered mRNA expression levels." (PMID 34576024, 2021). "In humans and mice, mutations in the Nbeal2 gene results in gray platelet syndrome (GPS), a rare inherited bleeding disorder characterized by thrombocytopenia, lack of α-granules within blood platelets and progressive development of bone marrow fibrosis." (PMID 31652790, 2019). "The Gray Platelet Syndrome in mouse and human is associated with an abolished gene function of Nbeal2 (NBEAL2), where primarily α-granule formation is severely impaired." (PMID 31171812, 2019). "Mutations in NBEAL2 (Neurobeachin-like protein 2) cause Gray Platelet Syndrome, with abnormalities in the biogenesis of thrombocytes and their secretory α-granules." (PMID 28814779, 2017). "Mutations in NBEAL2 cause Gray Platelet Syndrome (GPS), an autosomal recessive bleeding disorder characterized by macrothrombocytopenia and gray-appearing platelets due to lack of platelet alpha granules." (PMID 26950939, 2016). "Gray platelet syndrome (GPS) is a rare disease caused by homozygosity and compound heterozygosity for autosomal mutations on the NBEAL2 gene, which is characterized by a deficiency of platelet α-granules, bleeding symptoms." (PMID 39465716, 2024). "Gray platelet syndrome (GPS) is a serious congenital deficit of α granules (number and/or content) ordinarily due to mutations in the NBEAL2 gene." (PMID 33926054, 2021). "Mutations in NBEAL2 were recently shown to be the cause of the autosomal recessive form of Gray Platelet Syndrome (GPS)." (PMID 26950939, 2016). "Patient 11 had two unreported missense variants c.295C>T (p.Arg99Trp) and c.4169C>T (p.Ser1390Leu) on the NBEAL2 gene, which related to Gray platelet syndrome." (PMID 34237177, 2021). "Previous studies have indicated that gray platelet syndrome (GPS) is a rare platelet disorder characterized by abnormalities in α-granules and mutations in NBEAL2, featuring macrothrombocytopenia and a specific deficiency of α-granules and their associated contents." (PMID 40221859, 2025). "Recently, platelet RNA-seq successfully revealed abnormal splicing events in 1) NBEAL2, thus identifying the gene responsible for the Gray Platelet Syndrome, and, 2) the RNA-binding protein RBM8A, thus uncovering the gene responsible for the TAR (=thrombocytopenia and absent radii) syndrome." (PMID 23323973, 2013). "Inactivation of the BEACH (beige and chediak‐higashi) family member NBEAL2 in humans and mice results in the development of the gray platelet syndrome (GPS), a bleeding disorder characterised by macrothrombocytopenia and splenomegaly." (PMID 41111259, 2026). "Mutations in the human Nbeal2 gene can cause gray platelet syndrome (GPS), a bleeding 85 diathesis characterized by a lack of α granules in platelets." (PMID 35215885, 2022). "Mutations in the human NBEAL2 gene cause gray platelet syndrome (GPS), a bleeding diathesis characterized by a lack of α granules in platelets." (PMID 28783043, 2017).
Thrombocytopenia (6 papers, 2013 to 2025). A reduction in the number of circulating thrombocytes. "It is associated with enlarged platelets and mild thrombocytopenia with moderate to severe bleeding as a result of biallelic mutations in NBEAL2, the gene encoding the neurobeachin-like-2 protein." (PMID 31275945, 2019). "Tissue was analysed at 5-, 7-, and 14-days post-lesion (dpl) in WT and in Nbeal2-KO mice and at 7 dpl after chemically-induced thrombocytopenia." (PMID 41286446, 2025). "Among these, GP1BA (c.1591dup, c.1525C>T, and c.378C>G), ITGB3 (c.1394C>G), NBEAL2 (c.3796del), WAS (c.655G>T, deletions of exons 1-2), and MPL (c1511T>A) were notable for their association with severe thrombocytopenia and morphological platelet abnormalities." (PMID 40488176, 2025). "Loss of NBEAL2 function leads to grey platelet syndrome (GPS), a bleeding disorder characterized by macro-thrombocytopenia and α-granule-deficient platelets." (PMID 37349339, 2023). "Because in Nbeal2-KO mice, thrombocytopenia is not full, we assessed the presence of platelets within the SEZ vasculature ipsilateral and contralateral to the lesion." (PMID 41286446, 2025). "In contrast, thrombocytopenia without platelet tissue-infiltration, in Nbeal2 knockout mice, did not affect the brain’s progenitors." (PMID 41286446, 2025). "However, short-term, severe, thrombocytopenia led to a significant increase in the percentage of OLIG2+ cells, both in the control SEZ and at 7 dpl, compared to the WT and the Nbeal2-KO mice (magenta bar)." (PMID 41286446, 2025).
Macrothrombocytopenia (5 papers, 2016 to 2026). "Freson and coworkers also reported for two patients with macrothrombocytopenia that the GATA1 N-terminal zinc finger variants D218Y/G suppress NBEAL2 RNA and protein expression, leading to paucity of platelet α-granules." (PMID 36231035, 2022).
bleeding disorder (4 papers, 2016 to 2026). "Recessive mutations in the NBEAL2 gene lead to grey platelet syndrome (GPS), characterized by macrothrombocytopenia, α-granule-deficient platelets, bleeding disorders, and (in some cases) splenomegaly and progression to myelofibrosis." (PMID 37349339, 2023).
myelofibrosis (3 papers, 2016 to 2024). A partial or complete replacement of the bone marrow stroma by fibrous tissue. "However, whether this abnormality is directly dependent on NBEAL2 mutation rather than a consequence of compromised bone marrow homeostasis, associated with the progressive myelofibrosis, has never been investigated." (PMID 26987485, 2016).
autoimmune disease (2 papers, 2023 to 2024). A disorder resulting from loss of function or tissue destruction of an organ or multiple organs, arising from humoral or cellular immune responses of the individual to their own tissue constituents. "Our results thus show that NBEAL2 is involved in the regulation of CTLA-4 expression in conventional T cells and provide a rationale for considering CTLA-4-immunoglobulin therapy in patients with GPS and autoimmune disease." (PMID 37349339, 2023).
coronary artery disease (2 papers, 2025 to 2026). "Causal inference analyses suggest methylation-mediated coronary artery disease risk via NBEAL2 regulation, nominating biologically relevant targets while underscoring the need for larger multi-omics resources to refine mechanisms." (PMID 41890840, 2026). "Causal analyses supported cg08227773 methylation-mediated effects on both coronary artery disease risk (PSMR=2.91E-05, coloc PP.H4 =0.91) and NBEAL2 (Neurobeachin-like 2) expression (PSMR=9.13E-08, coloc PP.H4=0.69), a gene implicated in immune dysregulation." (PMID 41334702, 2025).
platelet disorder (2 papers, 2015 to 2024). "Furthermore, the NBEAL2 gene which is located near CCDC12 is already recognized in familial platelet disorders with a predisposition to MDS/AML." (PMID 26384344, 2015).
Alzheimer disease (1 paper, 2020). A progressive, neurodegenerative disease characterized by loss of function and death of nerve cells in several areas of the brain leading to loss of cognitive function such as memory and language. "Seven out of 18 genes are associated with neurological diseases: Alzheimer’s disease (CPT1A, SUFU, ZSWIM8, PDCD4), schizophrenia (HTT, NBEAL2) and Parkinson disease (PRDM13)." (PMID 32599769, 2020). "Interestingly, there were seven genes associated with neurological disorders, including Alzheimer’s disease (CPT1A, SUFU, ZSWIM8, PDCD4), schizophrenia (HTT, NBEAL2) and Parkinson’s disease (PRDM13)." (PMID 32599769, 2020).
autism (1 paper, 2010). Persistent deficits in social interaction and communication and interaction as well as a markedly restricted repertoire of activity and interest as well as repetitive patterns of behavior. "While some studies have reported positive findings on chromosome 13 for autism, attention has focused on the neurobeachin gene (NBEAL2), which lies in between our two regions and is, therefore, not supported by our data." (PMID 20678250, 2010).
Autoimmunity (1 paper, 2023). The occurrence of an immune reaction against the organism's own cells or tissues. "These include LRBA, a member of the same BEACH domain family as NBEAL2, recessive mutations of which cause autoimmunity and lymphocytic infiltration through defective CTLA-4 trafficking." (PMID 37349339, 2023). "NBEAL2 loss of function mutations lead to grey platelet syndrome, a condition characterised by α-granule-deficient platelets and, in a proportion of cases, by autoimmunity." (PMID 37349339, 2023). "To extend our knowledge on autoimmunity and immune abnormalities in patients with GPS, we investigate NBEAL2’s role in the immune system and particularly in T cells." (PMID 37349339, 2023). "Here authors show that NBEAL2 physically interacts with CTLA-4 in human T cells, and NBEAL2 deficiency leads to reduced CTLA-4 surface expression in effector T cells, but not regulatory T cells, thus tipping the balance towards autoimmunity." (PMID 37349339, 2023).
colon cancer (1 paper, 2024). "Mutations in KIAA1217, POLD1, PIEZO1, NBEAL2, DDX17, and PARP14 were significantly more prevalent in patients with colon cancer and PRShigh than in those with PRSlow." (PMID 38577604, 2024).
H1N1 virus infection (1 paper, 2022). "Here, we showed that Nbeal2 played an essential role in the immune response caused by H5N1 and H1N1 virus infection." (PMID 35215885, 2022).
head and neck cancer (1 paper, 2022). A primary or metastatic malignant neoplasm affecting the head and neck. "Nurobeachin like 2 (NBEAL2) plays a role in development and secretion of alpha granules containing growth factors and is a prognostic marker for head and neck cancer." (PMID 36582804, 2022).
keratoconus (1 paper, 2024). A degenerative, structural disorder of the eye, characterized by a cone-shaped protrusion of the cornea. "NBEAL2 encodes a cellular scaffold protein (2750 aa, 302 kDa), which is in the keratoconus library in NEIBank (neibank.nei.nih.gov)." (PMID 39238827, 2024).
mastocytosis (1 paper, 2026). A clonal myeloproliferative neoplasm characterized by the proliferation and accumulation of neoplastic mast cells in one or multiple organs or organ systems. "The relevance of our data is underscored by the fact that the NBEAL2 gene seems to be inactivated in mastocytosis or MCL patients." (PMID 41111259, 2026).
ovarian carcinoma (1 paper, 2012). A malignant neoplasm originating from the surface ovarian epithelium. "A set of eight biomarkers: NKIRAS1/RPL15, THRB, RBPS3 (CTDSPL), IQSEC1, NBEAL2, ZIC4, LOC285205 and FOXP1, was identified as the most prominent set capable to detect both early and late stages of ovarian cancer." (PMID 23202957, 2012).
systemic mastocytosis (1 paper, 2026). Systemic mastocytosis (SM) comprises a heterogeneous group of rare acquired and chronic hematological malignancies that are related to an abnormal proliferation of mast cells in tissue, including bone marrow, with or without skin involvement. "In patients with mast cell leukaemia (MCL), indolent systemic mastocytosis (ISM) and aggressive systemic mastocytosis (ASM), loss of heterozygosity (LOH) of chromosome region 3p21 leads to the loss of 10 genes, among them NBEAL2." (PMID 41111259, 2026).
thrombosis (1 paper, 2016). "Though initially considered as a plausible thrombosis modifier, this Nbeal2 mutation failed to suppress the synthetic lethal thrombosis on which the original ENU screen was based." (PMID 26950939, 2016).
cancer (9 papers, 2012 to 2026). A tumor composed of atypical neoplastic, often pleomorphic cells that invade other tissues. "As high ABCB1 surface levels are correlated with an oncogenic phenotype, our data show that Nbeal2 inactivation supports the development of MC neoplasms and probably also other cancer entities." (PMID 41111259, 2026). "Moreover, in many cancer diseases such as acute myeloid leukaemia (AML), damaging and therefore inactivating NBEAL2 mutations were identified." (PMID 41111259, 2026). "We selected novel epigenetic markers including NKIRAS1/RPL15, THRB RBPS3 (CTDSPL), IQSEC1, NBEAL2, ZIC4, LOC285205, CGGBP1, EPHB1 and FOXP1 that allowed detection of cancer in ovarian biopsies on all stages with sensitivity equal to (72 ± 11)% and specificity (94 ± 5)%." (PMID 23202957, 2012).
tumor (4 papers, 2015 to 2021). "The MDR included the CCDC12, NBEAL2, SETD2, KIF9 and KLHL18 genes, of which SETD2 was the most significantly underexpressed in tumour cells." (PMID 27282254, 2016).
infection (3 papers, 2017 to 2024). The state of being infected such as from the introduction of a foreign agent such as serum, vaccine, antigenic substance or organism. "Recent research has shown anomalies in the function of neutrophils and natural killer (NK) cells and impaired host defense after infection of Staphylococcus aureus in Nbeal2-deficient mice." (PMID 35215885, 2022). "Consistent with our qRT-PCR results, immunohistochemistry and western blotting using an antibody against Nbeal2 at 24 h post-infection further verified the increased expression of Nbeal2 in H5N1-infected P815 cells." (PMID 35215885, 2022). "Between 6 and 12 h post-infection, the Nbeal2 mRNA levels decreased in P815 cells infected with H1N1 virus, while they significantly increased in those infected with H5N1." (PMID 35215885, 2022). "The Nbeal2 mRNA expression in P815 cells infected with H1N1 or H5N1 virus peaked at 24 h post-infection before decreasing." (PMID 35215885, 2022). "From 18 to 24 h post-infection, the mRNA levels of Nbeal2 increased in P815 cells infected with either H1N1 or H5N1 virus." (PMID 35215885, 2022). "Four of these patients show evidence of abnormal susceptibility to infection, but a lack of comprehensive clinical data means this almost certainly represents an underestimate of the prevalence of immunological abnormalities in NBEAL2 deficiency." (PMID 28783043, 2017). "From the analysis of the transcriptomic profile, the Nbeal2 gene is more expressed by H5N1 infected mast cells, explaining why this infection tends to be more severe than that by H1N1." (PMID 39768136, 2024). "We next followed Nbeal2 transcription in H5N1- and H1N1-infected cells every 6 h upon infection in details." (PMID 35215885, 2022). "Remarkably, the knockdown of Nbeal2 significantly promoted the production of IL-1α, IP-10, IL-6, CCL-4 and TNF-α at 24 h post-infection in P815 cells infected with H1N1 virus and H5N1 virus." (PMID 35215885, 2022). "Consistent with the result of RNA-seq analysis, the Nbeal2 expression showed significant difference between H5N1- and H1N1-infected P815 cells at 12 h post-infection." (PMID 35215885, 2022). "The functions of the NBEAL2 protein have not been explored outside platelet biology, but there are reports of increased frequency of infection and abnormal neutrophil morphology in patients with GPS." (PMID 28783043, 2017). "In summary, for the first time, we established the roles of Nbeal2 in two IAV strain infections and the crosstalk between Nbeal2 regulation by IAV infection as well as its effect on innate immunity in MCs, which suggested that Nbeal2 may be a promising target for future therapeutic interventions." (PMID 35215885, 2022).
NBEAL2 also shares sentences with these, for which no sentence is quoted: Splenomegaly (3 papers); intestinal diseases (2); autoimmune lymphoproliferative syndrome (1); bone marrow fibrosis (1); cervical cancer (1); cognitive deficits (1); colitis (1); influenza (1); intestinal polyp (1); intestinal tumor (1); kidney (1); lupus (1); neurological diseases (1); Parkinson disease (1); sarcopenia (1); schizophrenia (1).